FABP4 (fatty acid binding protein 4)
Diseases named in the same sentence as FABP4 in open-access papers (continued):
Sharing a sentence is not in itself a finding about the gene and the disease.
tendinopathy (1 paper, 2018). "However, presently the increase in fat tissue in the tendinopathy and chronic ruptured tendons compared to the acute ruptured tendons was confirmed by the gene expression data, with an increased FABP4 and PPARγ expression in tendinopathy and chronic ruptured tendons." (PMID 29385715, 2018).
thalassemia major (1 paper, 2021). "However, the study about association of FABP4 and cardiac function in patients with thalassemia major is still limited." (PMID 34987673, 2021). "Inverse correlation of serum FABP4 and serum ferritin levels in patients with thalassemia major was demonstrated in our study." (PMID 34987673, 2021). "FABP4 levels could be a potentially useful clinical biomarker for cardiac dysfunction via metabolic and inflammatory pathways due to iron accumulation and toxicity in patients with thalassemia major." (PMID 34987673, 2021). "The role of FABP4, as one of a novel biomarker for metabolically driven low-grade and chronic inflammation, may provide a clue in these mechanisms that occurred in patients with thalassemia major." (PMID 34987673, 2021).
thymic lymphomas (1 paper, 2015). "The results from microarray-base gene expression analysis showing the down-regulation of LPL and FABP4 in mice with radiation-induced thymic lymphomas hinted at the involvement of these unknown immunosuppressive factors in thymic lymphomas pathogenesis." (PMID 25923834, 2015). "The levels of LPL and FABP4, both of which are involved in lipid uptake and metabolism, was down-regulated in the thymus, spleen and PBMC of mice with thymic lymphomas, compared to the levels in mice that did not receive radiation treatment." (PMID 25923834, 2015).
thyroid disorders (1 paper, 2022). "Defining the role of FABP4, fetuin-A and RBP4 presents a promising direction for the prevention and treatment of metabolic consequences accompanying thyroid disorders." (PMID 35448487, 2022). "Therefore, therapies targeting FABP4, fetuin-A and RBP4 may prove to be effective means of counteracting metabolic complications in thyroid disorders." (PMID 35448487, 2022).
thyroid tumor (1 paper, 2018). A benign or malignant neoplasm affecting the thyroid gland. "As for the CRABP1 paralog FABP4, its expression in thyroid tumors seems to be inversely correlated to the malignancy or aggressiveness of the tumors and has been used in general classifiers proposed to discriminate malignant from benign thyroid tissues." (PMID 29535811, 2018).
ulcerative colitis (1 paper, 2015). An inflammatory bowel disease involving the mucosal surface of the large intestine and rectum. "Meanwhile, stronger staining of FABP4, adipsin and adiponectin in the epithelial crypts of ulcerative colitis patients could be detected." (PMID 26687459, 2015).
viral myocarditis (1 paper, 2021). Myocarditis that is caused by an infection with a viral agent. "The DEGs for cardiomyocytes were primarily involved in viral myocarditis, cell adhesion molecules, and regulation of lipolysis in adipocytes (e.g., FABP4, NPPA, etc.)." (PMID 34514716, 2021).
vitiligo (1 paper, 2022). Generalized well circumscribed patches of leukoderma that are generally distributed over symmetric body locations and is due to autoimmune destruction of melanocytes. "In line with their findings, the authors observed a significant association between high FABP4 levels and the presence of MetS in present study's vitiligo patients." (PMID 34839983, 2022). "MetS was significantly more prevalent among vitiligo patients (p < 0.001) and associated with high FABP4 serum levels (p = 0.037)." (PMID 34839983, 2022). "In vitiligo patients, the high FABP4 serum levels were significantly associated with the presence of MetS (p = 0.037)." (PMID 34839983, 2022). "FABP4 level was a significantly good diagnostic test for early detection of vitiligo (p < 0.001)." (PMID 34839983, 2022). "Receiver Operating Characteristic (ROC) curve showed that FABP4 level was a significant-good diagnostic test for early detection of vitiligo with best cut off point 33.0 ng/mL, the sensitivity of 82%, specificity of 76%, and 0.863 area under the curve (p < 0.001)." (PMID 34839983, 2022). "In the present study, the authors investigated, for the first time, the possible role of FABP4 in vitiligo development through evaluation of its serum level in patients having NSV versus controls." (PMID 34839983, 2022). "In vitiligo patients, there were significant positive correlations between FABP4 serum levels and triglycerides (p = 0.047), cholesterol (p = 0.001) and LDL (p = 0.001) levels and negative correlation regarding HDL level (p = 0.009)." (PMID 34839983, 2022). "There was a significant elevation of FABP4 serum levels in vitiligo patients (46.78 ± 14.54 ng/mL) than controls (27.67 ± 7.65 ng/mL) (p < 0.001)." (PMID 34839983, 2022). "FABP4 may play an active role in vitiligo development and its targeting may have an appraising effect in clinical application in vitiligo management." (PMID 34839983, 2022). "The present study reported a significant increase in FABP4 circulating levels in vitiligo patients than matched peers, and these high concentrations were significantly associated with MetS in the studied cases, confirming that the pathogenesis of vitiligo has an immune-metabolic background." (PMID 34839983, 2022). "Therefore, the aim of this study was to evaluate the serum level of FABP4 in vitiligo patients and its relation to MetS." (PMID 34839983, 2022). "As vitiligo is considered one of the inflammatory diseases, the authors proposed that, in vitiligo, FABP4 may act at the interface of inflammatory and metabolic pathways." (PMID 34839983, 2022). "FABP4 may be a marker of vitiligo helping in its early diagnosis, but it does not appear to be useful for determining vitiligo severity, activity or associated MetS." (PMID 34839983, 2022). "However, FABP4 was not different according to the severity of vitiligo, as FABP4 serum level was not significantly correlated with VASI score (r = -0.21; p = 0.162)." (PMID 34839983, 2022).
tumor (302 papers, 2009 to 2026). "High FABP4 expression is associated with M2 polarization of tumor-associated macrophages (TAMs), enhancing the immunosuppressive microenvironment." (PMID 40717587, 2025). "FABP4 is primarily expressed in adipocytes, monocytes/macrophages, and tumor-associated stromal cells, regulating fatty acid uptake, transport, and metabolism, and participating in energy homeostasis, inflammatory responses, and cellular signal transduction." (PMID 40717587, 2025). "Lower FABP4 levels are associated with larger tumour size, presence of portal vein tumour thrombus (PVTT), and shorter OS and DFS." (PMID 41154605, 2025). "This immune regulatory function synergizes with metabolic reprogramming; for example, FABP4-mediated fatty acid β-oxidation enhances the M2 polarization of tumor-associated macrophages (TAMs), further inhibiting anti-tumor immune responses." (PMID 40717587, 2025). "FABP4 is implicated in the regulation of gene expression, cell proliferation, differentiation, and signal transduction in the context of tumor metastasis." (PMID 41034734, 2025). "Higher expression of FABP4 has been associated with increased cell proliferation, migration, and invasion, contributing to tumor growth and metastasis." (PMID 40870889, 2025). "FABP4 is also expressed in M2-like tumor-associated macrophages and plays a critical role in pro-tumor activity by promoting the IL-6/signal transducer and activator of transcription (STAT)-3 signaling pathway in a murine breast cancer model." (PMID 40017805, 2025). "Mechanistically, FABP4 mediates paracrine lipid transfer from tumor-associated adipocytes to cancer cells, fueling mitochondrial β-oxidation and upregulating stemness markers (e.g., ALDH1A1), thereby sustaining aggressive phenotypes." (PMID 40717587, 2025). "Lung cancer: FABP4 + macrophages support tumor growth through lipid metabolism and are associated with resistance to anti-PD1 therapy." (PMID 40717587, 2025). "Low FABP4 expression was associated with more aggressive tumour features and poor prognosis, establishing it as an independent prognostic factor." (PMID 41149452, 2025). "Immunohistochemistry shows that FABP4 expression is associated with stronger tumor invasiveness and poorer prognosis." (PMID 40718481, 2025). "To assess their blocking function using in vitro cellular studies, we identified that the 12G2-V9 variant exhibited significant inhibition of FABP4-mediated tumor migration and proliferation in wound healing assays." (PMID 39054536, 2024). "Our previous studies demonstrated that the deficiency of FABP4 inhibited E0771 tumor growth in syngeneic mouse models." (PMID 39054536, 2024). "As described in the following section, FABP4 is one of the most essential proteins responsible for lipid metabolism–associated tumor-promoting effects." (PMID 39085485, 2024). "FABP4 secreted by tumor-associated macrophages and circulating FABP4 secreted by dysfunctional adipocytes leads, via various signal transduction pathways, to enhanced stem cell-like phenotype and tumor progression." (PMID 38230225, 2024). "Differentially expressed genes associated with NAFLD-HCC specific tumor microenvironment were screened, of which FABP4 and VWF were featured by previous reports." (PMID 37950277, 2023). "While most studies have reported that elevated FABP4 levels are associated with increased tumor aggressiveness, other studies have observed that loss of FABP4 is related to increased progression and worse outcomes in some cancers." (PMID 36060264, 2022). "We generated a model of BALB/c nude mice bearing the tumours derived from FABP4-deficient BGC-823 cells delivered by tail vein injection; these animals received intraperitoneal injections of rosiglitazone or vehicle DMSO." (PMID 35198079, 2022). "Fatty acid-binding protein 4 (FABP4) has been reported to be associated with tumor progress and poor prognosis in various cancers." (PMID 36264920, 2022).
tumor (continued). "The association between FABP4 and immune cell infiltration was evaluated by Tumor Immune Estimation Resource (TIMER) database." (PMID 36264920, 2022). "In TNBC patients, elevated levels of FABP5 were correlated with tumor grade and poor prognosis, and higher amounts of tumor FABP4 expression were associated with significantly shorter disease-free survival and overall survival." (PMID 34948368, 2021). "The results indicated that ABCA8 and FABP4 were negatively correlated with tumor purity and were positively associated with six types of immune cells." (PMID 32685482, 2020). "High FABP3 and FABP4 expressions observed in non-small cell lung cancer were associated with tumor metastasis and negatively affect patient survival." (PMID 32422889, 2020). "FABP4 has been recently reported as hypoxia-regulated gene, and its expression in tumour endothelial cells is associated with increased angiogenesis, especially in low-grade stroma-rich tumours." (PMID 30765860, 2019). "Analysis of the data, specific to tumor compartment of patient samples revealed that a unique metabolic profile is associated with the expression of FABP4." (PMID 30050129, 2018). "When tumor subtype was considered, FABP4 positivity was associated with significantly shorter disease-free survival (p = 0.005) and overall survival (p = 0.041) in TNBC." (PMID 25751270, 2015). "It has been reported that loss of FABP4 is related to carcinoma progression; hence, FABP4 is suggested as a tumor suppressor protein." (PMID 25709631, 2014). "Furthermore, FABP4 is released from cancer-associated adipocytes after lipolysis induction and has an important role in tumor initiation and progression." (PMID 39458176, 2024). "Using in vitro tumor wound healing assays, we demonstrated that FABP4-enhanced tumor migration could be blocked by these variants, especially by V9." (PMID 39054536, 2024). "Within the TME, tumor-associated macrophages (TAMs) also show distinct upregulation of FABP4." (PMID 39085485, 2024). "If the cancer-associated adipocytes that release FABP4 are included in the adjacent normal tissue, tumor resection might reduce the serum FABP4 levels." (PMID 39458176, 2024). "Higher tumor grade and mortality were associated with more FABP4 expression in macrophages." (PMID 39513934, 2024). "In addition, the reduction in FABPs expression has been associated with tumor progression inhibition, while a high FABP4 expression is correlated with CRC metastasis and poor prognosis." (PMID 37760840, 2023). "Based on subgroup marker genes, the cell cluster highly expressing LGMN was annotated as M2 cells, the cell cluster with high expression of CXCL9 was annotated as M1 cells, and the cell cluster highly expressing FABP4 was annotated as non-tumor-associated macrophages (NTAMs)." (PMID 36969247, 2023). "Intracellular FABP4 is the one of the most critical players implicated in CAA-tumor cell interplay." (PMID 35899119, 2022). "In their study, adipocytes entrapped with a reactive oxygen species (ROS)-responsive DOX prodrug (pDOX) and rumenic acid (RA) could cause tumor cells damage through the activation of lipid metabolic pathway mediated by fatty acid-binding protein 4 (FABP4)." (PMID 34834304, 2021). "Multiple logistic regression analysis showed that the expression of FABP4 was significantly associated with tumor size (odds ratio = 2.115, 95% confidence interval [CI] = 1.104−4.204, p = 0.024) and mitotic index (odds ratio = 2.623, 95% confidence interval [CI] = 1.408−4.889, p = 0.002)." (PMID 34558731, 2021). "However, FABP4 expression was found to be associated with clinicopathological features such as large tumor size, multiple lesions, and high AFIP‐Miettinen risk stratification." (PMID 34558731, 2021). "Furthermore, FABP4 level, tumor size, mitotic index, and high AFIP‐Miettinen risk were independent prognostic factors in GISTs." (PMID 34558731, 2021).
tumor (continued). "FABP3 is a tumor suppressor, whereas FABP4, FABP5, and FABP7 are associated with poor survival." (PMID 31941087, 2020). "Because FABP4 is a key factor implicated in adipocyte-tumor cell interaction and FAO metabolism, we investigated whether avocatin B affected the uptake of FFA by AML cells." (PMID 30442990, 2018). "However, when tumor subtype was considered, there were also significant associations between FABP4 positivity and shorter DFS (p = 0.005) and shorter OS (p = 0.041) in TNBC." (PMID 25751270, 2015). "FABP4 regulates lipid metabolism, enhancing fatty acid transport and activating pro-tumorigenic pathways, which promote the accumulation of tumor-associated macrophages (TAMs) and myeloid-derived suppressor cells (MDSCs), leading to immune suppression and tumor immune evasion." (PMID 39610918, 2024). "Notably, FABP4 deficiency significantly reduced LA-mediated tumor migration." (PMID 39513934, 2024). "We considered that FABP4 may be involved in regulation of tumour-associated macrophage function, lipid droplet catabolism, fatty acid metabolism for energy supply and insulin resistance, and may potentially influence tumour development and progression." (PMID 36532833, 2022). "FABP4 drives lipid metabolic reprogramming and tumor microenvironments that support cancer cell proliferation and metastatic potential." (PMID 42158110, 2026). "The interaction terms of FABP‐4 with tumor stage, with time to CRC diagnosis, and with diabetic status all had p‐values >0.4 (data not shown); no further subgroup analyses were conducted for these variables." (PMID 40857027, 2026). "FABP4 and vimentin expression was increased in proximity to the tumor, while caveolin-1, CD44, MMP9, and adiponectin showed minimal or no changes." (PMID 41596770, 2026). "In Ewing sarcoma, suppression of the FLI1 gene leads to a moderate increase in FABP4 expression, potentially influencing tumor metabolism and microenvironment interactions." (PMID 40852589, 2025). "After tumor development 1 week after implantation, anti-FABP4 mAbs were administered, at 400 μg, 800 μg, and 1,200 μg, via i.p. injection." (PMID 41392988, 2025). "Clinically, TNBC tumor tissues displayed notable down-regulation of FABP4 and PPARG in comparison with normal tissues." (PMID 40604951, 2025). "FABP4, mainly expressed in breast stroma, especially in adipose tissue, likely supported neighboring tumor cell lymphovascular invasion through secretion from adipocytes." (PMID 40106183, 2025). "FABP4 modulates B-cell functionality within tumor microenvironments and potentially mediates crosstalk with immunosuppressive populations (e.g., tumor-associated macrophages, regulatory T-cells), fostering tumor-permissive niches." (PMID 40948800, 2025). "Among the 96 cases analyzed, 46 cases (47.9%) showed FABP4-positive tumor cells near adipose tissue." (PMID 40106183, 2025). "Enhanced fatty acid oxidation: FABP4 promotes the uptake of free fatty acids by tumor cells, maintaining mitochondrial function." (PMID 40717587, 2025). "FABP4 promotes angiogenesis in tumors, and in vivo, the application of FABP4 siRNA exhibited anti-angiogenic and anti-tumor effects." (PMID 41419794, 2025). "Functional studies showed that secreted FABP4 augmented HCC tumor growth by modulating the PI3K/AKT/β-catenin signaling pathway through its interaction with ITGB1." (PMID 41392988, 2025). "Next, we investigated the therapeutic potential of the anti-FABP4 mAb in suppressing tumor growth in a MASLD-HCC mouse model induced by orthotopic injection of RIL-175 mouse HCC cells into the liver of mice fed a HFD for 13 weeks." (PMID 41392988, 2025). "FABP4 also contributes to cancer proliferation, and FABP4 inhibitors have been demonstrated to block tumor growth in xenograft mice." (PMID 40759794, 2025).